MIR296 (microRNA 296)
Synonyms: hsa-mir-296; MIRN296; miRNA296; mir-296
Gene: MicroRNA gene on chromosome 20 (58,817,615 to 58,817,694, reverse strand). Ensembl gene ENSG00000284040.
Gene Ontology:
Biological process: miRNA-mediated post-transcriptional gene silencing
Cellular component: RISC complex
Diseases named in the same sentence as MIR296 in open-access papers:
MIR296 is named in the same sentence as 3 diseases in open-access papers, as found by Europe PMC text mining. Sharing a sentence is not in itself a finding about the gene and the disease. The quoted sentences say what the papers report.
lung carcinoma (1 paper, 2017). "Aberrant expression of MIR296 was previously related to gastric, bladder, and lung cancer." (PMID 28814981, 2017).
prostate carcinoma (1 paper, 2020). A carcinoma that arises from epithelial cells of the prostate gland. "In addition, MIR296 targeting PIN1, another gene involved in tumor development, suppresses cell proliferation and growth in prostate cancer cells." (PMID 32582296, 2020).
tumor (2 papers, 2020). "Through the negative regulation of the expression of these genes, MIR296 exerts its action as a tumor suppressor." (PMID 32582296, 2020).